NLRP12 (NLR family pyrin domain containing 12)
Description:
Plays an essential role as an potent mitigator of inflammation. Primarily expressed in dendritic cells and macrophages, inhibits both canonical and non-canonical NF-kappa-B and ERK activation pathways. Functions as a negative regulator of NOD2 by targeting it to degradation via the proteasome pathway. In turn, promotes bacterial tolerance. Also inhibits the RIGI-mediated immune signaling against RNA viruses by reducing the E3 ubiquitin ligase TRIM25-mediated 'Lys-63'-linked RIGI activation but enhancing the E3 ubiquitin ligase RNF125-mediated 'Lys-48'-linked RIGI degradation. Also acts as a negative regulator of inflammatory response to mitigate obesity and obesity-associated diseases in adipose tissue (By similarity).
Synonyms: NALP12; PYPAF7; RNO; RNO2; Monarch1; PAN6; CLR19.3; FCAS2
Tractability: No criterion of Open Targets' tractability assessment is met for any kind of drug.
Gene: Protein-coding gene on chromosome 19 (53,792,139 to 53,824,403, reverse strand). Ensembl gene ENSG00000142405.
Subcellular location: Cytoplasm
Pathways (Reactome):
Disease: SARS-CoV-2 activates/modulates innate and adaptive immune responses
Gene Ontology:
Molecular function: protein binding; cysteine-type endopeptidase activator activity; protein-macromolecule adaptor activity
Biological process: negative regulation of canonical NF-kappaB signal transduction; negative regulation of cytokine production; negative regulation of inflammatory response; negative regulation of interleukin-1 production; negative regulation of interleukin-6 production; negative regulation of non-canonical NF-kappaB signal transduction; negative regulation of signal transduction; negative regulation of Toll signaling pathway; positive regulation of MHC class I biosynthetic process; positive regulation of non-canonical NF-kappaB signal transduction; regulation of canonical NF-kappaB signal transduction; positive regulation of inflammatory response; positive regulation of interleukin-1 beta production; regulation of inflammatory response; regulation of interleukin-18 production; signal transduction
Cellular component: cytoplasm; nucleus; cytosol
Genetic constraint (gnomAD): Loss-of-function variants: 107 observed, 94.01 expected, observed/expected ratio (o/e) 1.14, 90% interval 0.97 to 1.34. The upper end of that interval is the gene's LOEUF score, 1.34, which puts it in group 5 of 6, group 1 being the genes least tolerant of losing a copy. Missense variants: 1,518 observed, 1,416.5 expected, observed/expected ratio (o/e) 1.07, 90% interval 1.03 to 1.12. Synonymous variants: 611 observed, 599.57 expected, observed/expected ratio (o/e) 1.02, 90% interval 0.95 to 1.09.
Homologues: Orthologues: chimpanzee NLRP12 (99% identical), macaque NLRP12 (94% identical), dog NLRP12 (80% identical), pig NLRP12 (77% identical), rabbit NLRP12 (76% identical), rat Nlrp12 (75% identical), mouse Nlrp12 (73% identical). Paralogues in human: NLRP3 (47% identical), NLRP4 (31% identical), NLRP9 (31% identical), NLRP14 (27% identical), NLRP1 (27% identical), NLRP2 (24% identical), NLRP7 (24% identical), NLRP5 (24% identical), NLRC5 (23% identical), NLRP13 (23% identical), NLRC3 (23% identical), NLRP6 (22% identical), and 8 more.
Diseases named in the same sentence as NLRP12 in open-access papers:
NLRP12 is named in the same sentence as 136 diseases in open-access papers, as found by Europe PMC text mining. Sharing a sentence is not in itself a finding about the gene and the disease. The quoted sentences say what the papers report.
colitis (47 papers, 2013 to 2024). Inflammation of the colon. "In a different study, a UCAC mouse model that had NLRP12 cut out was more likely to get severe colitis and even tumors linked to colitis than wild-type mice." (PMID 39582536, 2024). "Mice deficient in Nlrp12 showed increased susceptibility to azoxymethane (AOM) plus dextran sodium sulfate (DSS)–induced colitis and colitis-associated colorectal tumorigenesis." (PMID 37581937, 2023). "We previously showed that increased colitis susceptibility of Nlrp12–/– mice is associated with higher activation of NF-κB and ERK pathways." (PMID 37581937, 2023). "Nlrp12–/– mice are susceptible to colitis, colorectal tumorigenesis, autoimmune encephalomyelitis, and hepatocellular carcinoma, and exhibit protection against bacterial infection and hemolytic disease." (PMID 37581937, 2023). "Nlrp12-deficient mice have increased susceptibility to colitis which can be partially mitigated with antibiotic treatment." (PMID 35313917, 2022). "Studies have shown that Nlrp12−/− mice are more susceptible to DSS-induced colitis and have a lower diversity of intestinal microbial communities than WT mice, but the performance of germ-free (GF)-Nlrp12−/− mice is similar to that of GF-WT mice." (PMID 35954484, 2022). "Nlrp12−/− mice are highly susceptible to colitis and colitis-associated colorectal cancer, whereas they are resistant to Salmonellosis." (PMID 33525590, 2021). "The loss of protective gut commensal strains of the family Lachnospiraceae and an increase in the abundance of colitogenic strains of the family Erysipelotrichaceae in Nlrp12‐deficient mice causes colonic inflammation." (PMID 33665894, 2021). "Mice deficient in Nlrp12 are highly susceptible to chemically induced colitis and colorectal tumorigenesis." (PMID 31941025, 2020). "The absence of NLRP12 in mice resulted in a severe uncontrolled inflammation that rendered NLRP12-deficient mice highly susceptible to experimental colitis and inflammation-induced tumorigenesis." (PMID 32796686, 2020). "Recent studies suggest that altered gut microbiota predisposes susceptibility to colitis and obesity in Nlrp12-/- mice." (PMID 31941025, 2020). "Some animal study showed that Nlrp12−/− mice were highly susceptible to colitis and colitis-associated colon cancer." (PMID 32245519, 2020). "Meanwhile, NLRP12-deficient mice are highly sensitive to dextran sulphate sodium (DSS)-induced colitis and exhibit exacerbated colonic inflammation." (PMID 31061672, 2019). "NLRP12-/- mice also have the same characteristics, reflecting susceptibility to colitis and microbiome dysbiosis, which indicates the key role of NLRP12 in maintaining intestinal homeostasis." (PMID 31614539, 2019). "Foremost, genetic ablation of Nlrp12 renders mice highly susceptible to colitis and colitis-associated colorectal cancer, while being resistant to Salmonellosis6." (PMID 30559449, 2018). "Similar research has revealed that mice deficient in the intestinal inflammatory regulator NLRP12 possess a dysbiotic microbiome and exacerbated colitis." (PMID 30271409, 2018). "Consistent with the regulatory function for NLRP12 in innate immune cells, Nlrp12−/− mice were shown to be highly susceptible to inflammatory diseases of intestine, such as experimental colitis and colon cancer." (PMID 29403486, 2017). "As observed for NLRP6, NLRP12 plays a central role in protecting against chemically induced colitis and inflammation-associated tumorigenesis." (PMID 25071778, 2014). "Studies have shown that Nlrp12−/− mice are more susceptible to both DSS-induced colitis and AOM/DSS-induced tumorigenesis, indicating a tumor suppressor function for NLRP12 in CAC." (PMID 24474192, 2014). "Akin to NLRP6, loss of NLRP12 in mice causes more severe colitis, in line with the role of NLRP12 as negative regulator of NF-κB and MAPK pathways." (PMID 24886810, 2014). "In fact, NLRP12 deficient were more susceptible to DSS-induced colitis and AOM-DSS-induced colon cancer." (PMID 25071778, 2014).
colitis (continued). "Furthermore, mice with NLRP12 deficiency showed enhanced DSS-induced colitis and AOM/DSS-induced colon cancer due to dysbiosis and increased NF-κB signaling." (PMID 37191444, 2023). "Interestingly, these bacteria belong to family Erysipelotrichaceae, which has been associated with severe colitis in Nlrp12−/− mice." (PMID 33339337, 2020). "NLRP12 deficiency, in a dextran sodium sulfate (DSS)-induced colitis model, promotes colon inflammation, decreases gut microbiota diversity and increases colitogenic bacteria, such Erysipelotrichaceae family, depicting a protective role of NLRP12 in IBD." (PMID 32903730, 2020). "Nlrp12 deficiency decreases microbiome diversity and increased susceptibility to colitis." (PMID 31186453, 2019). "It has been reported that NLRP12 can dampen inflammatory responses after colitis induction and suppress colitis-associated tumorigenesis, and that induction of colitis in NLRP12-deficient mice can lead to enhanced cytokine and chemokine release and promote hyperplasia and tumorigenesis." (PMID 27105524, 2016). "It has been reported that NLRP12 could exert both pro- and anti-inflammatory functions, and that NLRP12 deficient mice are more susceptible to DSS induced colon inflammation and tumorigenesis." (PMID 27105524, 2016). "However, NLRP12 was also shown to have inflammasome‐independent, anti‐inflammatory functions during Salmonella infection, and loss of NLRP12 in mice increases susceptibility to colon inflammation, colorectal tumor development and atypical neuroinflammation." (PMID 37700491, 2023). "Moreover, mice deficient in NLRP12 were more susceptible to colitis and colorectal tumorigenesis." (PMID 35563010, 2022). "However, it would be of great interest to investigate the factors that may influence the balance between NLRP12 anti-inflammatory effect and the inflammasome associated pro-inflammatory effect during the development of colitis." (PMID 27105524, 2016). "Two recent studies have connected NLRP12 with the gut microbiota in the contexts of colon inflammation and obesity." (PMID 38745196, 2024). "Previous studies have reported that NLRP12 protein can dampen inflammatory responses in DSS-induced mice colitis." (PMID 40225939, 2024). "Serum exosomes derived from patients with H. pylori-positive gastritis can attenuate the expression of MCP-1 and MIP-1α in intestinal epithelial cells via the NLRP12-Notch signaling pathway, thereby ameliorating dextran sodium sulfate-induced colitis." (PMID 38619276, 2024). "For example, transfer of the CD4+CD45RBhiNlrp12−/− T cells into the immunodeficient mice exacerbated severe colitis and showed that NLRP12 was an intrinsic negative regulator of T cell activation." (PMID 37191444, 2023). "Previous studies showed higher activation of NF-κB, ERK, and STAT3 in the colon of Nlrp12–/– mice during acute DSS-induced colitis." (PMID 37581937, 2023). "The involvement of PRDM1 in NLRP12 expression have been investigated in skin sensitization and colitis, in which the expression of NLRP12 was also negatively associated with PRDM1 expression." (PMID 34956178, 2021). "NLRP12-deficient mice, a mouse model with functional relevance to TRAF3, is highly susceptible to colitis and colitis-associated colon cancer." (PMID 34257589, 2021). "Transfer of naïve Nlrp12-/- T cells into immunodeficient Rag-/- mice also elicited exacerbated colitis." (PMID 31941025, 2020). "Experimental studies demonstrated that NLRP12 protects mice from colitis, colorectal tumorigenesis, and experimental autoimmune encephalomyelitis (EAE)." (PMID 30990169, 2019). "Our results demonstrated that the induction of colitis significantly decreased colonic NLRP12 expression, which is consistent with studies that demonstrated the involvement of NLRP12 in the occurrence and development of UC." (PMID 31061672, 2019).
colitis (continued). "A recent study determined a key role for NLRP12 in dictating intestinal inflammation and preventing colitis; therefore, we examined the expression of NLRP12 by western blot and qPCR analyses." (PMID 31061672, 2019). "In conclusion, QCWZD can protect against DSS-induced colitis by modulating gut microbiota and promoting NLRP12 expression, which occurs via the inhibition of the activity of the TLR4/Blimp-1 axis." (PMID 31061672, 2019). "Previous studies showed that Nlrp12−/− mice are highly vulnerable to inflammatory diseases such as experimental colitis and colorectal tumor development." (PMID 30150571, 2018). "To further elucidate the mechanism of NLRP12 involvement in the DSS induced colitis, we first examined the expression pattern of NLRP12 upon DSS stimulation in murine dendritic cells." (PMID 27105524, 2016). "It has been reported that Blimp-1 participates in the development of colitis, and that Blimp-1 inversely correlates with NLRP12 expression during cell differentiation." (PMID 27105524, 2016). "We, therefore, set out to investigate the interaction between Blimp-1 and NLRP12 in DSS-induced mice colitis." (PMID 27105524, 2016). "Taken together, the results suggest that the TLR4-Blimp-1 axis promotes DSS induced experimental colitis through the down-regulation of NLRP12." (PMID 27105524, 2016). "Two independent studies proposed that NLRP12 acts as a tumor suppressive molecule ex vivo and in in vivo animal models of colitis and colitis-induced CRC." (PMID 25071785, 2014). "Altogether, these results underscore the importance of anti-inflammatory signals provided by NLRP12 in maintaining colonic homeostasis and protecting from colitis and colon tumorigenesis." (PMID 25071785, 2014). "In support of our finding are two previous reports that a CAPS mouse transgenic model carrying human NLRP3 pathogenic mutations maintain homeostasis in the gut microbiota and are resistant to experimental colitis, whereas NLRP12 defect results in microbiome disturbance and colitis." (PMID 38343435, 2023). "Nlrp12 is also involved in maintaining gut microbiota homeostasis, promoting the growth of beneficial bacteria, and playing a protective role in colitis and related tumors, which may be related to its anti-inflammatory activity." (PMID 35954484, 2022). "However, the suppression of pro-inflammatory cytokines, (e.g., via anti-TNF and anti-IL-6R antibody treatment) restores Nlrp12−/− induced changes in gut microbiota and alleviates the severity of colitis." (PMID 35954484, 2022). "NLRP12 plays a crucial role in both the hematopoietic and nonhematopoietic compartment for controlling overt inflammation, colitis and colitis-associated tumorigenesis." (PMID 32796686, 2020). "NLRP12 was demonstrated to interfere with the release of proinflammatory cytokines, which participated in intestinal inflammatory reaction and promoted the development of colitis." (PMID 31061672, 2019). "Non-surprisingly, Nlrp12 deficient mice developed enhanced inflammatory symptoms in T-cell-mediated autoimmune diseases such as colitis and atopic dermatitis." (PMID 30150571, 2018). "Therefore, Nlrp12−/− T cells developed enhanced inflammatory symptoms in T-cell-mediated autoimmune diseases such as colitis and atopic dermatitis." (PMID 29403486, 2017). "Previous studies have shown that NLRP12 may act as a negative regulator during DSS-induced mice colitis." (PMID 27105524, 2016). "The increased inflammatory responses observed in NLRP12 deficient mice during DSS-induced colitis are correlated with increased canonical and non-canonical NF-κB activation signaling." (PMID 25071778, 2014). "Further, NLRP12 deficiency in non-haematopoietic intestinal cells was in part responsible for increased susceptibility to DSS-induced colitis, especially in later phases of the disease." (PMID 25536194, 2014).
colitis (continued). "Of these NLRs, NLRP12 is the prototypical member and has been shown to negatively regulate components of both canonical and non-canonical NF-κB pathways in vitro and more recently found to display this role in vivo in colitis and colon cancer models." (PMID 23577168, 2013). "In addition, Nlrp12 is found to be downregulated in colitis patients." (PMID 35954484, 2022). "Consequently, NLRP12-deficient mice were highly susceptible to colitis and colitis-associated colorectal cancer through the increase in noncanonical NF-κB activation and expression of Cxcl13 and Cxcl12 as target genes that were associated with cancer." (PMID 34571825, 2021). "Also, NLRP12 in colon associated cancer and colitis serves as a negative regulator of the canonical and non- canonical pathways of NF-kB signaling." (PMID 31186453, 2019). "On the other hand, NLRP12 could also exert inhibitory effect during the development of colitis." (PMID 27105524, 2016). "Research indicates that the serum exosomes lead to an upregulation of NLRP12 expression in intestinal epithelial cells, which inhibits the expression of chemokine MCP-1 and MIP-1α in these cells, alleviating DSS-induced colitis." (PMID 39569001, 2024). "gulates NLRP12, inhibits the release of IL-1β and TNF-α, and reduces DSS-induced inflammatory response in colitis in mice." (PMID 32547403, 2020). "In this study, we sought to identify the upstream regulator of NLRP12 involvement in the development of DSS-induced colitis, and found that TLR4-mediated up-regulation of Blimp-1 led to the down-regulation of NLRP12 expression in DSS-induced colitis." (PMID 27105524, 2016). "In this study, we sought to investigate the role of NLRP12 in DSS-stimulated proinflammatory response in dendritic cells and mice colitis, and the molecular mechanisms involved in the development of the inflammation." (PMID 27105524, 2016). "Moreover, TLR4 was implicated in Blimp-1 upregulation, which subsequently leads to Blimp-1-mediated NLRP12 downregulation and IL-1β secretion in DSS-induced colitis mice." (PMID 34299198, 2021). "In particular, generating bone marrow chimeras, the authors showed that Nlrp12 in immune, rather than in epithelial cells, is critical for the protection against colitis and CAC and this effect appeared to be related to the Nlrp12-mediated suppression of canonical NF-kB and Erk in macrophages." (PMID 29868004, 2018). "Although deficiency in other inflammasome components, including ASC, caspase-1, and IL-18, also led to dysbiosis and exacerbated colitis, deficiency in NLRC4, NLRP10, NLRP12, and AIM2 had no impact on the susceptibility of WT mice to colitis upon cohousing." (PMID 26925061, 2016). "NLRP12 anti-inflammatory function during DSS-induced mice colitis seems to be not related to NLRP12 inflammasome assembly." (PMID 27105524, 2016). "However, the upstream factors involved in regulation of NLRP12 expression and function during colitis have not yet been identified." (PMID 27105524, 2016). "However, the upstream regulator of NLRP12 during the development of colitis has still not been identified." (PMID 27105524, 2016). "NLRP12 (Monarch-1) is a prototypical member of this sub-group that negatively regulates both canonical and noncanonical NF-κB signaling in biochemical assays and in colitis and colon cancer models." (PMID 23577168, 2013). "NLRP6 and NLRP12 have been found to attenuate NF-kB and MAPK in models of colitis and CRC, NLRC3 has been shown to act as a negative regulator of TLR and DNA-induced cytokine production." (PMID 26378020, 2015).